PIP (prolactin induced protein)
Synonyms: GCDFP-15; SABP; GCDFP15; GPIP4; BRST-2
Tractability: Antibody: its Gene Ontology location is reachable by antibodies, with high confidence; UniProt places it where antibodies can reach, with medium confidence; UniProt predicts a signal peptide or a membrane-spanning region.
Gene: Protein-coding gene on chromosome 7 (143,132,077 to 143,139,739, forward strand). Ensembl gene ENSG00000159763.
Subcellular location: Secreted
Pathways (Reactome):
Transport of small molecules: Miscellaneous transport and binding events
Gene Ontology:
Molecular function: aspartic-type endopeptidase activity; identical protein binding; IgG binding; protein binding; actin binding
Biological process: detection of chemical stimulus involved in sensory perception of bitter taste; negative regulation of T cell apoptotic process; positive regulation of gene expression; proteolysis; regulation of immune system process
Cellular component: extracellular exosome; extracellular region; nucleus
Genetic constraint (gnomAD): Loss-of-function variants: 2 observed, 4.94 expected, observed/expected ratio (o/e) 0.41, 90% interval 0.16 to 1.26. That is too few expected variants to judge how well the gene tolerates losing a copy. Missense variants: 83 observed, 92.12 expected, observed/expected ratio (o/e) 0.9, 90% interval 0.75 to 1.08. Synonymous variants: 39 observed, 39.08 expected, observed/expected ratio (o/e) 1, 90% interval 0.77 to 1.3.
Homologues: Orthologues: chimpanzee PIP (97% identical), macaque PIP (76% identical), guinea pig PIP (62% identical), rabbit PIP (60% identical), dog PIP (49% identical), mouse Pip (47% identical), rat Pip (43% identical).
Diseases named in the same sentence as PIP in open-access papers:
PIP is named in the same sentence as 120 diseases in open-access papers, as found by Europe PMC text mining. Sharing a sentence is not in itself a finding about the gene and the disease. The quoted sentences say what the papers report.
breast carcinoma (86 papers, 1999 to 2025). "Breast cancer (BC) is the most common cancer in women, and a higher level of prolactin-induced protein (PIP) is associated with better responses to adjuvant chemotherapy." (PMID 40003884, 2025). "In the GeparTrio trial (NCT00544765), a phase III randomized neoadjuvant study for breast cancer treatment, immunohistochemistry was used to examine the expression of GCDFP-15 (known as PIP) in 602 pre-therapeutic core biopsies obtained from patients." (PMID 37759471, 2023). "One of the specific and sensitive markers in breast cancer is prolactin-induced protein or GCDFP-15, which is a 15 kDa protein that is initially detected in cystic fluid from cystic mastopathy." (PMID 37383152, 2023). "Prolactin-induced protein (PIP) is considered as a highly promising prognostic factor in breast cancer treatment." (PMID 37759471, 2023). "Some studies indicate that prolactin-inducible protein (PIP) is expressed to varying degrees in more than 90% of breast cancers (BCs)." (PMID 37759471, 2023). "The prolactin inducible protein (PIP) is expressed to varying degrees in more than 90% of breast cancers (BCs)." (PMID 33777801, 2021). "Remarkably, PRL induces the expression of prolactin-inducible protein (PIP), a component of milk that is widely expressed in breast cancer (BC) and prostate cancer (PC) promoting cancer cell growth and proliferation." (PMID 26691922, 2015). "The PIP (prolactin-inducible protein) gene has been shown to be expressed in breast cancers, with contradictory results concerning its implication." (PMID 19262752, 2009). "For this study we selected seven breast cancer-associated genes [mam, CEA, CK19, PIP, muc1, PSE, Erb (BM only) and EpCAM (PBL only)] known to be over-expressed in metastatic breast cancer compared to control lymph nodes." (PMID 18289390, 2008). "Notably, Dermcidin (DCD) and prolactin inducible protein (PIP) serve as biomarkers, with DCD linked to breast cancer and lymph nodes, while PIP is overexpressed in breast and prostate cancer." (PMID 40305328, 2025). "PIP, also known as gross cystic disease fluid protein 15 (GCDFP-15), is commonly used in the clinic as a breast cancer biomarker to assist in characterizing metastases of unknown origin." (PMID 34736512, 2021). "Feature map of a representative sample from a BRCA (breast cancer) patient assigns the 2 out of 3 biomarker genes, SCGB2A2 and PIP, with the top 10 feature weights." (PMID 40662781, 2025). "Prolactin-inducible protein (PIP), also known as gross cystic disease fluid protein 15 (GCDFP-15), has emerged as a subject of significant interest in recent years due to its potential role as a specific marker in breast cancer." (PMID 37759471, 2023). "The cluster‐defined genes, PIP and ANKRD30A, were exclusively expressed in P8 CSF‐CTCs, indicating sufficient evidence to diagnose the primary site as breast cancer, sweat/salivary gland cancer, or prostate cancer." (PMID 33377642, 2020). "Prolactin-inducible protein (PIP), also referred to as gross cystic disease fluid protein 15 (GCDFP-15), has been a trending topic in recent years due to its potential role as a specific marker in breast cancer." (PMID 37759471, 2023). "Using these gene markers [mam, CEA, CK19, PIP, muc1, PSE, Erb (BM only) and EpCAM (PBL only)] we analyzed 215 PBL samples and 177 BM samples from patients with T1-T3 primary breast cancer without clinical evidence of metastatic disease." (PMID 18289390, 2008).
breast tumors (16 papers, 1998 to 2025). "A similar pattern of expression was observed when the grafts were examined for expression of prolactin-induced protein, a protein whose expression occurs in the majority of ER+ breast tumours." (PMID 23088371, 2012). "The most regulated gene in this process, prolactin-induced protein (PIP), was further studied using immunohistochemistry of breast tumors and xenograft models." (PMID 22817771, 2012).
lobular carcinoma (8 papers, 2007 to 2026). "Several genes encoding proteins involved in actin, calcium and metal ion binding were downregulated (MYBPC1, DST, PIP, CA2), and some genes with the same function (BGN, ADAM12) were upregulated in lobular carcinomas." (PMID 17389037, 2007).
primary Sjögren’s syndrome (4 papers, 2013 to 2025). "For example, the AQP5 C-terminus was found to interact with prolactin-inducible protein (PIP) in control mice (Jcl:ICR, CLEA Japan), but interact with major urinary protein 4 in non-obese diabetic (NOD) mice (model for Sjögren’s syndrome)." (PMID 35514349, 2022).
Anxiety (3 papers, 2016 to 2019). Intense feelings of nervousness, tension, or panic often arise in response to interpersonal stresses. "Overall, this study found that the PiP intervention produced significantly greater improvements than an active control in parenting risk and protective factors associated with adolescent risk for depression and anxiety." (PMID 31418422, 2019). "Conditional effects analyses revealed that among parents whose adolescents reported lower (SCAS-C≤12.42) and average (12.42<SCAS-C<46.68) levels of anxiety at baseline, PiP led to greater increases in PRADAS scores compared with the control condition (see Multimedia Appendix 4)." (PMID 29351895, 2018). "Contrary to expectations, at 12-month follow-up, there was no robust indication that PiP significantly reduced adolescent depression and anxiety symptoms as reported by either parents or adolescents, compared with the active-control intervention." (PMID 31418422, 2019). "As a universal prevention program involving a primarily community-based sample, we found that PiP did not demonstrate any short-term effect on adolescent depressive or anxiety symptoms, likely due to a “floor effect” (symptom levels were low at baseline for most participants)." (PMID 29351895, 2018).
cystic mastopathy (2 papers, 2014 to 2023). "prolactin-inducible protein, PIP) is a 15 kDa protein that was originally detected in the cystic fluid from cystic mastopathy." (PMID 25070172, 2014).
keratoconus (2 papers, 2014 to 2025). A degenerative, structural disorder of the eye, characterized by a cone-shaped protrusion of the cornea. "The expression of Prolactin-Induced Protein may serve as a biomarker for Keratoconus, a degenerative disease of the cornea." (PMID 40358859, 2025).
neuroendocrine tumors (2 papers, 2020 to 2022). "Among these, known biomarkers for MB (FSTL5), and other tumor types such as neuroendocrine tumors (ENO2, FMOD, ART3, COL6A3) and PIP, were found to be significantly up-regulated (dark green)." (PMID 32466393, 2020).
Obesity (2 papers, 2022 to 2025). Accumulation of substantial excess body fat. "Prolactin-inducible protein (PIP) was lower in the women with obesity compared to the women with normal weight." (PMID 40565086, 2025).
atherosclerosis (1 paper, 2023). A disease characterized by the build-up of fatty material and calcium deposition in the arterial wall resulting in partial or complete occlusion of the arterial lumen.
dementia (1 paper, 2021). Loss of intellectual abilities interfering with an individual's social and occupational functions. "While only a small number of PiP participants with dementia were able to participate in the follow-up interviews, their voices and those of their family/carers are given equal weight in critiquing the hospital experience." (PMID 34574951, 2021).
dental caries (1 paper, 2016). The decay of a tooth, in which it becomes softened, discolored, and/or porous. "In addition, we found prolactin inducible protein (PIP) and myoglobin might also be candidate biomarkers of dental caries." (PMID 27527350, 2016).
invasive breast carcinoma (1 paper, 2014). A carcinoma that infiltrates the breast parenchyma. "Gross Cystic Disease Fluid Protein-15(GCDFP-15)/Prolactin-Inducible Protein (PIP) expression is associated with invasive breast cancer." (PMID 25423363, 2014).
nasal polyps (1 paper, 2022). "hsa-mir-27a-3p may promote the occurrence of inflammation and the formation of nasal polyps by regulating the expression of AZGP1, NCF2, CCL13, MUC7, PIP, and STATH." (PMID 36059464, 2022).
oligoasthenoteratozoospermia (1 paper, 2024). A form of male infertility that is characterized by a combination of low number or oligozoospermia, poor motility or asthenozoospermia, and abnormal shape or teratozoospermia of sperms. "Key proteins associated with sperm function, such as NPC intracellular cholesterol transporter 2 (NPC2), galectin-3-binding protein (LGALS3BP), lipocalin-1 (LCN1), and prolactin-inducible protein (PIP), show reduced expression in oligoasthenoteratozoospermia (OAT)." (PMID 39685846, 2024).
tumor (74 papers, 1998 to 2025). "Immunohistochemistry of primary tumor tissue was performed for eight proteins: COL6A6, DCD, GBP4, KLHL41, KRT9, PIP, SCGB1D2, SCGB2A2." (PMID 34757537, 2022). "Recently, RT–PCR assays with tumour-specific gene markers such as CK19, CEA, MUC1, PIP, Mapsin and mammaglobin B have been widely used to detect occult metastasis in cancer patients." (PMID 14583780, 2003). "Interestingly, there were four tumor suppressors significantly stimulated after YB, namely, deleted in malignant brain tumor 1 (DMBT1), mucin-7 (MUC7), cysteine-rich secretory protein 3 (CRISP3), and prolactin-inducible protein (PIP)." (PMID 25873979, 2015). "The prolactin-inducible protein (PIP/GCPD15) is believed to originate from a limited set of tissues, including breast and salivary glands, and has been applied as a clinical marker for the diagnosis of metastatic tumours of unknown origin." (PMID 10576657, 1999). "We show that tumor cells derived from wild-type animals do not proliferate when transplanted in a Postn-null environment but that this growth defect is rescued by the overexpression of active Notch or the AR target gene prolactin-induced protein (PIP/GCDFP-15)." (PMID 25592291, 2015).
cancer (26 papers, 2003 to 2025). A tumor composed of atypical neoplastic, often pleomorphic cells that invade other tissues. "Two known sweat biomarkers that are used for cancer prognosis are Dermcidin (DCD) and Prolactin Inducible Protein (PIP)." (PMID 40028481, 2023).
infection (14 papers, 2013 to 2025). The state of being infected such as from the introduction of a foreign agent such as serum, vaccine, antigenic substance or organism. "Bacteriophages that require YjaE for infection (CHPC3, CHPC24, CHL92, bil67) are not affected by disruption of the pip gene, and bacteriophages which require the PIP protein (CHPC180, c2) can still infect yjaE mutants." (PMID 25186244, 2014).
genetic disorders (1 paper, 2019). "Still, as many as 636 PIP-modulating or -binding proteins have not, as of yet, been linked with human genetic disorders, indicating that they are either indispensable for early embryonic development or functionally redundant." (PMID 31413155, 2019).
neurological disease (1 paper, 2019). "In the future, inhibitors or activators of the PIP enzymes and PIP-binding proteins associated with neurological disease are likely to emerge as viable therapeutics." (PMID 31413155, 2019).
PIP also shares sentences with these, for which no sentence is quoted: adenocarcinoma (9 papers); gastric cancer (8); metastatic tumors (8); ovarian carcinoma (7); metastatic carcinoma (5); prostate carcinoma (5); lung carcinoma (4); melanoma (4); Paget disease (4); apocrine carcinomas (3); depression (3); dry eye (3); gastrointestinal tumors (3); invasive lobular carcinoma (3); lung adenocarcinoma (3); mucinous adenocarcinoma (3); triple-negative breast carcinoma (3); urothelial carcinoma (3); Alzheimer disease (2); breast adenocarcinoma (2); carcinomas of the salivary glands (2); colorectal adenocarcinoma (2); Hypertension (2); ovarian tumor (2); prostate adenocarcinoma (2); rectal adenocarcinoma (2); renal cell carcinoma (2); salivary duct carcinoma (2); urachal adenocarcinomas (2); adenosquamous carcinoma (1).
A further 70 diseases each share a sentence with PIP in 1 paper.